SPHK1 (sphingosine kinase 1)
Diseases named in the same sentence as SPHK1 in open-access papers (continued):
Sharing a sentence is not in itself a finding about the gene and the disease.
bladder cancer (15 papers, 2015 to 2024). "Thus, we believe c-Src plays a key role in harnessing PD-L2 and FAK activation underlying the promoting effect of SPHK1 on bladder cancer progression." (PMID 39284838, 2024). "Similarly, elevated SPHK1 expression is associated with metastatic sublines generated from two bladder cancer cell lines (T24 and 253J)." (PMID 39284838, 2024). "In this study, we demonstrated the driver role of SPHK1 in promoting in vitro migration and invasion as well as lung metastases of bladder cancer in which S1PR-elicited Akt/β-catenin signaling network is the key downstream effector for the mechanism of action." (PMID 39284838, 2024). "Many studies have indicated that SPHK1 is involved in several types of cancer development, however, a little is known in bladder cancer." (PMID 39284838, 2024). "In prostate and bladder cancer cells, systemic SPHK1/S1P signal through SiPR2 promotes lung metastasis via repressing the breast cancer metastasis suppressor 1 (BRMS1)." (PMID 39063133, 2024). "In vitro experiments provided strong evidence for the important role of the SphK1/S1P axis in the progression and chemoresistance of bladder cancer." (PMID 39595959, 2024). "Overall, our data strengthen the pertinent role of PD-L2 in SPHK1 promoting bladder cancer progression." (PMID 39284838, 2024). "On the other hand, we demonstrated that FDA-approved SPHK1 inhibitor Gilenya® (FTY720) can successfully suppress bladder cancer metastasis by in vitro and in vivo approaches." (PMID 39284838, 2024). "Here, we unveil the clinical relevance of SPHK1 in bladder cancer progression and the driver role in bladder cancer metastasis." (PMID 39284838, 2024). "Although there are no literature data on the content of S1P in UBC, several reports found an increased expression of SphK1 in bladder cancer compared with this in healthy adjacent tissue, which is in line with the results of our study." (PMID 39595959, 2024). "The TCGA database analysis was utilized for analyzing the clinical relevance of SPHK1 in bladder cancer." (PMID 39284838, 2024). "It shows that SPHK1 can regulate PD-L2 gene expression through Akt/β-catenin-axis in bladder cancer cell lines." (PMID 39284838, 2024). "Based on our evidence, we are optimistic about the synergy of SPHK1 inhibitor with PD-L2 inhibitor in bladder cancer treatment." (PMID 39284838, 2024). "Here, by analyzing bladder cancer TCGA database, although small percentage of SPHK1 gene amplification was detected, a significantly elevated SPHK1 expression in cancer tissues compared with normal tissues as well as paired samples." (PMID 39284838, 2024). "It was also reported that the overexpression of SphK1 alleviated the inhibitory effect of miR-613 and miR-125b-5p on the proliferation, migration, and invasion of bladder cancer cells." (PMID 39595959, 2024). "Our preliminary immunohistochemical analysis conducted on human bladder cancer samples has shown a positive IHC mucosa signal for LL-37 and SphK1 in cancer tissues." (PMID 35806446, 2022). "Using immunohistological staining, we showed high expression of hCAP-18/LL-37 and sphingosine kinase 1 (the enzyme that forms S1P from sphingosine) in human bladder cancer cells." (PMID 35806446, 2022). "For instance, tumor suppressive miRNA miR-125b-5p can target SphK1 to inhibit invasion and migration of bladder cancer cells." (PMID 33400245, 2021). "Our study demonstrated that the increased expression of SPHK1 and SPHK1 was a prognostic biomarker in bladder cancer." (PMID 34692520, 2021). "The expression levels of INHBA and SPHk1 were all markedly upregulated for bladder cancer both in vivo and in vitro." (PMID 34692520, 2021). "In human bladder cancer cells, miR-125b silenced SphK1 and inhibited cell proliferation and migration." (PMID 33465049, 2021). "A previous study also showed that miR-125b inhibited bladder cancer cell proliferation and migration by targeting SphK1." (PMID 35187068, 2021).
bladder cancer (continued). "miR163 and miRNA 125b can inhibit bladder cancer proliferation and migration through targeting SPHK1." (PMID 34692520, 2021). "An elevated level of miR-125b inhibits cell growth and migration and induces cell cycle arrest in the G1 phase, with a further study showing miR-125b targeting SphK1 and inhibiting bladder cancer progression." (PMID 35187068, 2021). "Based on the significant clinical prevalence of SPHK1 in bladder cancer progression and the functional role of SPHK1 in cell migration, invasion, and metastasis, we further explore the potential targeted therapeutic regimen of SPHK1 using clinically relevant xenograft model." (PMID 39284838, 2024). "These in vitro data support the potential impact of SPHK1 elevation on bladder cancer progression." (PMID 39284838, 2024). "Taken together, SPHK1 plays a potent driver role in bladder cancer progression." (PMID 39284838, 2024). "Moreover, we demonstrated the inhibitory effect of FDA-approved SPHK1 inhibitor FTY720 on bladder cancer metastasis from both in vitro and in vivo models." (PMID 39284838, 2024). "Through CRISPR/Cas9 knockout (KO) and constitutive activation (CA) strategies on SPHK1 in the bladder cancer cells, we demonstrated the potential downstream target could be programmed cell death 1 ligand 2 (PD-L2)." (PMID 39284838, 2024). "Notably, a co-expression of SphK1 and hCAP-18/LL-37 in bladder-cancer-affected tissue was also confirmed." (PMID 35806446, 2022). "Collectively, those data strongly suggest that both SphK1 and hCAP-18/LL-37 might be recognized as molecules affecting bladder cancer initiation and progression." (PMID 35806446, 2022). "MiR‐613 exerts tumor‐suppressing effects by directly targeting SphK1 in bladder cancer." (PMID 32343052, 2020). "Although clinical prevalence of SPHK1 expression in bladder cancer is highly significant, the detailed biologic actions and molecular mechanisms of SPHK1 in bladder cancer development are not fully characterized." (PMID 39284838, 2024). "In this study, we performed bioinformatic analyses of bladder cancer database and unveiled significant high expression of SPHK1 but not SPHK2 with clinical BS subtype, a typically invasive cancer, or LI subtype that is associated with chemo resistant." (PMID 39284838, 2024). "Moreover, we further examined the efficacy of FDA-approved SPHK1 inhibitor (i.e., FTY720) in reducing bladder cancer metastasis using in vivo orthotopically metastatic xenograft model." (PMID 39284838, 2024).
Cerebral ischemia (15 papers, 2015 to 2025). Restriction of arterial blood supply to the brain associated with insufficient oxygenation to support the metabolic requirements of the tissue. "Cerebral ischemia/reperfusion induced a strong, rapid, and transient increase of mRNA expression of the gene encoding for the S1P generating kinase SphK1." (PMID 31165772, 2019). "SphK1 was induced in microglia after cerebral ischemia, and the knockdown of SphK1 decreased IL17A production after oxygen/glucose deprivation." (PMID 37239854, 2023). "Mechanistically, SPHK1 expression has been revealed to be transcriptionally activated by FoxO3, a transcription factor, during cerebral ischemia/reperfusion injury." (PMID 37773702, 2023). "Although this study suggests the importance of SPHK1 in cerebral ischemia based on its mRNA upregulation, a functional role of SPHK1 needs to be clarified." (PMID 26576074, 2015). "Sphingosine kinase-1 (Sphk1-1, EC 2.7.1.91) is a regulator of pro-survival signalling, and its alterations have been observed in Alzheimer’s disease, brain ischemia and other neurological disorders." (PMID 25056275, 2015). "Interestingly, SPHK1 upregulation is responsible for cerebral ischemia‐reperfusion injury by promoting ER stress and inflammation." (PMID 37773702, 2023). "We hypothesize that endothelial SphK1/S1P signaling can increase NOS activity following cerebral ischemia, leading to dilation of local vasculature and thus reducing leukocyte adhesion and platelet aggregation, leading to improve patient prognosis." (PMID 31814336, 2020). "In vitro and in vivo models of cerebral ischemia, in addition to mTOR and NLRP3 inflammasome, PRNP, sphingosine kinase 1 (SphK1), DJ-1 and other signals participate in the regulation of neuroinflammation through autophagy as well." (PMID 37548945, 2024). "To study the functions of miR-19a/b-3p, SPHK1, FoxO3, and SIRT1 in cerebral ischemia, we firstly measured their expression levels during ischemia/ reperfusion (I/R)." (PMID 34051800, 2021). "NO synthesis has not been adequately studied in the context of the role of Sphk1/S1P on cerebral ischemia prognosis, and thus, our research has the potential to identify novel therapeutic avenues for future treatment development." (PMID 31814336, 2020). "Our study indicates that SphK1-SIP axis may potentiate neuroinflammatory responses and mediate brain damage through neuronal apoptosis, and DSCXQ could suppress the activity of SphK1-SIP axis to protect brain tissue in cerebral ischemia." (PMID 34026822, 2021). "our study clearly indicate that SphK1-SIP axis may potentiate neuroinflammatory responses and mediate brain damage in neuronal apoptosis, and DSCXQ suppressed the activity of SphK1-SIP axis to protect brain tissue in cerebral ischemia." (PMID 34026822, 2021). "In summary, apart from mTOR, AMPK and NLRP3, other signals, such as Sphk1, DJ-1, LRRK2 could modulate autophagy to participate in microglia polarization as well as inflammatory mediators’ production, thus affecting neuroinflammatory processes in cerebral ischemia, AD, TBI and other CNS diseases." (PMID 37548945, 2024).
osteosarcoma (15 papers, 2017 to 2025). A usually aggressive malignant bone-forming mesenchymal neoplasm, predominantly affecting adolescents and young adults. "Our data suggesting that SphK1/S1P signaling activation is associated with HIF-1α expression in osteosarcoma are in line with our previous findings in prostate and renal cell carcinoma cell models." (PMID 35158767, 2022). "Targeting SphK1 via hsa-miR-3677 has also been shown to inhibit the progression of human osteosarcoma cells." (PMID 36635678, 2023). "Collectively, these data suggesting that SphK1/S1P signaling is required for the regulation of HIF-1α in osteosarcoma are in line with our previous findings in prostate and renal cell carcinoma cell models." (PMID 35158767, 2022). "Sphingosine kinase 1 (SphK1) expression and activity are elevated in human osteosarcoma (OS) and is a promising target of therapy." (PMID 35115496, 2022). "The relationship between SphK1/S1P signaling and hypoxia was further validated in vitro in various osteosarcoma cell lines exposed to hypoxic conditions." (PMID 35158767, 2022). "We found that SphK1 activity was dramatically augmented in osteosarcoma with over a 50-fold increase in S1P production (431 pmoles/min/mg versus 6.6, p = 0.023)." (PMID 35158767, 2022). "In osteosarcoma cells, sphingosine kinase 1 (Sphk1) undergoes up-regulation due to hypoxia and activation of hypoxia-related molecular pathway, known as hypoxia-inducible factor 1α (HIF-1α)." (PMID 33652780, 2021). "Our data suggest that the SphK1/S1P signaling might represent a potential target to investigate in osteosarcoma patients, considering that fingolimod, which inhibits SphK1 and the S1P1 receptor, is now reconsidered for repurposing in cancer." (PMID 35158767, 2022). "Importantly, age-adjusted multivariate analyses showed that GLUT-1, SphK1 and S1P1 were associated with an increased risk of death (OS) depending on the osteosarcoma location (long versus flat bones)." (PMID 35158767, 2022). "By silencing SphK1, miR-124 inhibited proliferation and invasion of osteosarcoma (OS) cells." (PMID 33465049, 2021). "Moreover, miR-506-3p induced mesenchymal-to-epithelial transition and inhibited autophagy by regulation of SPHK1 (sphingosine kinase 1) in osteosarcoma cells." (PMID 33621206, 2021). "Sphingosine kinase 1 (SphK1) is a potential therapeutic target for human osteosarcoma (OS)." (PMID 32203055, 2020). "In all sets of TMA samples (130 cases of osteosarcoma), immunohistochemical analysis showed the hypoxic marker GLUT-1, SphK1 and S1P1 were expressed in tumors." (PMID 35158767, 2022). "Although the strength of linear correlation between SphK1 and GLUT-1 was weak, it was statistically extremely significant for all osteosarcomas (p = 0.005 for percentage of stained cells and p = 0.001 for IRS score)." (PMID 35158767, 2022). "Here we report that SphK1 and the S1P1 receptor are involved in HIF-1α accumulation in hypoxic osteosarcoma cells." (PMID 35158767, 2022). "miR-124 inhibited cell growth and invasion in osteosarcoma cells by targeting ROR2, SPHK1, Rac1 and B7-H3." (PMID 29113367, 2017). "Because we previously reported that the SphK1/S1P pathway is a regulator of both HIF-1α and HIF-2α during hypoxia in multiple cancer cell lineages, we evaluated its relevance with regard to HIF-1α expression in osteosarcoma cells." (PMID 35158767, 2022). "The expression of SphK1 in osteosarcoma had never been reported until this work." (PMID 35158767, 2022). "The Sphingosine kinase-1/Sphingosine 1-Phosphate (SphK1/S1P) signaling pathway is overexpressed in various cancers, and is instrumental for the adaptation to hypoxia in a number of solid tumor models, but no data are available in osteosarcoma." (PMID 35158767, 2022).
osteosarcoma (continued). "Interestingly, in contrast to classical chemotherapy, the dual SphK1 and S1P1 inhibitor FTY720 remarkably reduced cell proliferation to the same extent in normoxic and hypoxic conditions in all osteosarcoma cell lines, suggesting that efficacy of FTY720 was related to its anti-HIF-1α effect." (PMID 35158767, 2022). "Of note, there were no statistical differences of SphK1 and S1P1 (percentage of stained cells or IRS score) between the osteosarcoma sites." (PMID 35158767, 2022). "Studies have demonstrated that the Sphingosine kinase-1/Sphingosine 1-Phosphate (SphK1/S1P) signaling pathway regulates the expression of the HIF-1 transcription factor in a number of solid tumor models, but no data are available in osteosarcoma characterized by hypoxia." (PMID 35158767, 2022).
pulmonary hypertension (14 papers, 2015 to 2025). Increased pressure within the pulmonary circulation due to lung or heart disorder. "Adding further complexity, hypoxia-induced pulmonary hypertension is ameliorated by SPHK1 deficiency." (PMID 39899071, 2025). "SPHK1 is expressed in VSMCs, and its deficiency reduces proliferation and protects from pulmonary hypertension." (PMID 39899071, 2025). "SphK1-deficient mice are also less likely to develop pulmonary arterial hypertension than wild-type mice, and pulmonary arterial smooth muscle cells of SphK1-deficient mice are less likely to proliferate than those of wild-type mice." (PMID 38255229, 2024). "Inhibition of SphK1 reduced cell proliferation and pathological indications of vascular remodeling in vivo, suggesting the role of SphK1 in causing pulmonary hypertension." (PMID 26539114, 2015). "Moreover, verteporfin, an inhibitor of YAP1, reduces the S1P-induced proliferation of pulmonary arterial smooth muscle cells and hypoxia-induced pulmonary arterial hypertension, indicating that YAP1 is associated with the development of SphK1-induced pulmonary hypertension." (PMID 38255229, 2024). "S1P levels in serum are increased in patients with pulmonary hypertension, and the expression levels of both SphK1 and SphK2 in remodeled pulmonary arteries are also increased." (PMID 38255229, 2024). "We aimed to examine the specific roles of SPHK1 in PASMCs during pulmonary hypertension (PH) progression." (PMID 36498853, 2022). "SphK1 and S1P were elevated in lungs of patients with PH as well as in animal models of hypoxia-mediated pulmonary hypertension (HPH)." (PMID 28352271, 2017). "Recent studies have demonstrated that the expression of sphingosine kinase 1, the enzyme that catalyses formation of the bioactive lipid, sphingosine 1-phosphate, is increased in lungs from patients with pulmonary arterial hypertension." (PMID 27063355, 2016). "SphK1/S1P axis plays a significant role in the development of pulmonary arterial hypertension (PAH) by promoting PASMC proliferation, which is a major contributor to pulmonary vascular remodeling." (PMID 26317340, 2015). "The SphK1/S1P processes trigger hypoxia-induced vasoconstriction in human pulmonary arterial smooth muscle cells through Ca2+ dynamics due to TRPC and Ca2+ sensitization caused by Rho-kinase, probably resulting in pulmonary hypertension." (PMID 38255229, 2024). "Our previous studies showed that SPHK1 was upregulated in PASMCs isolated from patients with PAH and that the genetic deletion of Sphk1 in mice or the pharmacological inhibition of SPHK1 activity reduced hypoxia-induced pulmonary hypertension (PH) in mice and rats." (PMID 36498853, 2022). "It has been proved that SphK1 is involved in the occurrence of pulmonary arterial hypertension (PAH) based on the over-expression of SphK1 in vascular smooth muscle cells (VSMC) and lymphocytes of patients with PAH, and the symptoms of PAH were alleviated in SphK1 knockout mice rather than SphK2." (PMID 34737701, 2021). "As the most effective SphK1 inhibitor so far, PF-543 can inhibit inflammation in RA model, ulcerative colitis model and mouse pulmonary hypertension hypoxia model in vivo and in vitro, mainly by inhibiting the release of inflammatory cytokines and the change of cell biological function." (PMID 34737701, 2021). "Therefore, our findings with PF-543 suggest an important role for sphingosine kinase 1 in the development of hypertrophy in pulmonary arterial hypertension." (PMID 27063355, 2016). "Interestingly, recent research suggests that two important kinases, sphingosine kinase 1 (SphK1) and sphingosine kinase 2 (SphK2), are primary therapeutic targets for pulmonary hypertension." (PMID 26539114, 2015). "Therefore, we assessed the effect of the sphingosine kinase 1 selective inhibitor, PF-543 and a sphingosine kinase 1/ceramide synthase inhibitor, RB-005 on pulmonary and cardiac remodelling in a mouse hypoxic model of pulmonary arterial hypertension." (PMID 27063355, 2016).
pulmonary hypertension (continued). "SphK1 and S1P levels are markedly augmented in the lungs and pulmonary arterial smooth muscle cells of patients with pulmonary hypertension compared with healthy subjects, whereas SphK2 levels are not." (PMID 38255229, 2024). "SphK1 was shown to be upregulated in patients with pulmonary arterial hypertension (PAH) and its genetic deletion and pharmacologic inhibition protected against the development of hypoxia-mediated pulmonary hypertension (HPH) in mice (doi: 10.1164/rccm.201401-0121OC)." (PMID 37608809, 2023).